CPAP (centrosome assembly and centriole elongation protein)
Description:
Plays an important role in cell division and centrosome function by participating in centriole duplication. Inhibits microtubule nucleation from the centrosome. Involved in the regulation of slow processive growth of centriolar microtubules. Acts as a microtubule plus-end tracking protein that stabilizes centriolar microtubules and inhibits microtubule polymerization and extension from the distal ends of centrioles. Required for centriole elongation and for STIL-mediated centriole amplification. Required for the recruitment of CEP295 to the proximal end of new-born centrioles at the centriolar microtubule wall during early S phase in a PLK4-dependent manner. May be involved in the control of centriolar-microtubule growth by acting as a regulator of tubulin release.
Synonyms: CENP-J; CENPJ; LAP; LIP1; BM032; SASS4; SCKL4; Sas-4; MCPH6
Tractability: Small molecule: a structure with a bound ligand is known. PROTAC: ubiquitination databases record sites on it.
Gene: Protein-coding gene on chromosome 13 (24,882,276 to 24,922,889, reverse strand). Ensembl gene ENSG00000151849.
Subcellular location: Cytoplasm, cytoskeleton, microtubule organizing center, centrosome; Cytoplasm, cytoskeleton, microtubule organizing center, centrosome, centriole
Subcellular location (Human Protein Atlas): Centrosome; Acrosome
Pathways (Reactome):
Cell Cycle: AURKA Activation by TPX2; Loss of Nlp from mitotic centrosomes; Loss of proteins required for interphase microtubule organization from the centrosome; Recruitment of NuMA to mitotic centrosomes; Recruitment of mitotic centrosome proteins and complexes; Regulation of PLK1 Activity at G2/M Transition
Organelle biogenesis and maintenance: Anchoring of the basal body to the plasma membrane
Gene Ontology:
Molecular function: gamma-tubulin binding; identical protein binding; protein binding; protein domain specific binding; protein kinase binding; transcription coactivator activity; tubulin binding
Biological process: astral microtubule nucleation; centriole elongation; centriole replication; microtubule polymerization; positive regulation of centriole elongation; positive regulation of centriole replication; positive regulation of establishment of protein localization; positive regulation of G1/S transition of mitotic cell cycle; positive regulation of receptor signaling pathway via JAK-STAT; regulation of centriole replication; cell division; cilium assembly; microtubule nucleation; positive regulation of spindle assembly; regulation of mitotic spindle organization; positive regulation of DNA-templated transcription; positive regulation of organelle assembly
Cellular component: centriole; centrosome; cytoplasm; procentriole replication complex; cytosol; gamma-tubulin small complex; ciliary basal body
Genetic constraint (gnomAD): Loss-of-function variants: 106 observed, 132.28 expected, observed/expected ratio (o/e) 0.8, 90% interval 0.68 to 0.94. The upper end of that interval is the gene's LOEUF score, 0.94, which puts it in group 4 of 6, group 1 being the genes least tolerant of losing a copy. Missense variants: 1,437 observed, 1,570.8 expected, observed/expected ratio (o/e) 0.91, 90% interval 0.88 to 0.96. Synonymous variants: 491 observed, 553.38 expected, observed/expected ratio (o/e) 0.89, 90% interval 0.82 to 0.96.
Homologues: Orthologues: chimpanzee CENPJ (99% identical), macaque CENPJ (92% identical), dog CENPJ (80% identical), rabbit CPAP (76% identical), mouse Cpap (73% identical), guinea pig CPAP (73% identical), rat Cenpj (72% identical), pig CPAP (70% identical), zebrafish cpap (30% identical), Drosophila melanogaster Sas-4 (19% identical). Paralogues in human: TCP10L (4% identical).
Diseases named in the same sentence as CPAP in open-access papers:
CPAP is named in the same sentence as 32 diseases in open-access papers, as found by Europe PMC text mining. Sharing a sentence is not in itself a finding about the gene and the disease. The quoted sentences say what the papers report.
microcephaly (54 papers, 2012 to 2025). A congenital or acquired developmental disorder in which the circumference of the head is smaller than normal for the person's age and sex. "In this study, we investigated four consanguineous families with congenital microcephaly and identified three novel variants in CPAP, WDR62, and ASPM." (PMID 41555927, 2025). "Work by Phan and colleagues found that microcephaly‐associated mutations in the centrosomal genes CEP63 and CPAP cause a prolonged mitosis phenotype in neuronal progenitor cells in a mouse model for primary microcephaly." (PMID 40257113, 2025). "This is further supported by the fact that many genes associated with microcephaly encode centrosome proteins (CPAP, CEP152, CEP135, STIL, and CDK5RAP2) involved in centriole biogenesis and centrosome maturation." (PMID 39412222, 2025). "Cerebral organoids with the natural CPAP microcephaly mutation show smaller size caused by depletion of the cortical neural progenitor radial glial cells (RGCs), and early neuronal differentiation, probably via the action of the cilium disassembly complex." (PMID 37222855, 2023). "A mutation in the CPAP TCP domain that causes microcephaly in humans has been shown to decrease the affinity of CPAP to STIL." (PMID 31115335, 2019). "Crystal structures of this complex reveal an unusual, all-β structure adopted by the TCP domain and explain how a microcephaly mutation in CPAP compromises complex formation." (PMID 24052813, 2013). "Mutation of Centrosomal-P4.1-associated protein (CPAP) leads to Seckel syndrome with microcephaly." (PMID 37222855, 2023). "Despite several independent CPAP mutations have been identified in microcephaly patients, the underlying mechanism is unknown." (PMID 34049587, 2021). "To date, several independent CPAP mutations have been sequenced in microcephaly patients whose mechanisms underlying microcephaly remained unknown." (PMID 32457578, 2020). "Seckel syndrome with microcephaly is caused by mutation of centrosomal-P4.1-associated protein (CPAP), which might reduce the population of neural progenitor cells during brain development." (PMID 29937727, 2018). "In addition to cilia formation, the control of cilia disassembly is also critical in determining cortical growth, for example mutations in Cenpj or centrosomal-P4.1-associated protein (CPAP) cause dwarfism, microcephaly and intellectual disability through a depletion of the cortical stem cell pool." (PMID 33604340, 2021). "Importantly, these observations could, potentially, also help better explain the molecular mechanisms of aberrant CPAP expression/function-associated microcephaly, centriole duplication, mitotic and spindle positioning errors and ciliopathies." (PMID 34135376, 2021). "While a direct link between microcephaly and spindle orientation defects remains to be definitely established, our data provide an explanation how interfering with CPAP function can have consequences for spindle architecture." (PMID 40514430, 2025). "This study identifies novel variants in CPAP, WDR62, and ASPM and further delineates the mutational landscape of microcephaly-associated genes in the Pakistani population." (PMID 41555927, 2025). "Recently, specific brain organoids for congenital microcephaly have been generated, which have WDR62, ASPM, CDK5RAP2, and CPAP mutations." (PMID 36518994, 2022). "So far, three independent centrosome-related BOs have been generated from microcephaly patient iPSCs carrying mutations in CDK5RAP2, CPAP and ASPM." (PMID 34049587, 2021). "Centrosomal-P4.1-associated protein (CPAP protein) is related to microcephaly, and its mutation can cause Seckel syndrome and microcephaly." (PMID 33195219, 2020). "In this line, complete ablation of CPAP/Sas-4 was required to view evident microcephaly phenotypes in the mouse brain, suggesting that mouse neural progenitor cells (NPCs) are not as susceptible as human cells." (PMID 32457578, 2020).
microcephaly (continued). "Here we show that Cenpj, also known as CPAP, a microcephaly gene, is a transcriptional target of Ascl1 in the embryonic cerebral cortex." (PMID 25753651, 2015). "CPAP (MCPH6) and STIL (MCPH7) are required for centriole assembly, but it is unclear how mutations in them lead to microcephaly." (PMID 24052813, 2013). "Only a small set of conserved centriolar proteins is essential for centriole assembly and some of these proteins, like CPAP and STIL, have been linked to microcephaly in humans." (PMID 24052813, 2013). "For example, mutations in the centriolar proteins CPAP and STIL cause a syndrome known as microcephaly, in which the brain is smaller than normal." (PMID 24052813, 2013). "Centrosomal-P4.1-associated protein (CPAP) is a centriole wall protein required for the assembly and recruitment of PCM proteins to the centrosome; mutations in the CPAP gene can cause Seckel syndrome and microcephaly." (PMID 34539790, 2021). "Also, mutations in STIL that reside in the CPAP and SAS6 interacting motifs have also been identified in patients with microcephaly, although the significance of these alterations remains to be determined." (PMID 31115335, 2019). "Indeed, causal genetic defects for MCPH, such as MCPH1, CENPJ/CPAP, CEP213/CDK5RAP2, ASPM, WDR62, CEP135, CEP63 and STIL, encode centrosome or spindle-associated proteins, providing a further link between microcephaly and centrosomal-spindle function." (PMID 26908596, 2016). "Strikingly, most mouse models of microcephaly where the candidate genes (CDK5RAP2, CPAP, ASPM, Wdr62, and Plk4) were either completely ablated or highly overexpressed have invariably displayed apoptosis as a prominent mechanism for causing NPCs depletion and microcephaly." (PMID 32457578, 2020). "A number of microcephaly genes have been identified, including ASPM, microcephalin/BRIT1, CDK5RAP2/Cep215, CENPJ/CPAP, SIL/STIL, WDR62, and NDE1 (refs 3, 4, 5)." (PMID 27553190, 2016). "Although CPAP and STIL are known to bind each other, how they interact on a molecular level to form centrioles—and how this interaction is disrupted in microcephaly—is not well understood." (PMID 24052813, 2013). "Cumulatively, these findings reinforce the importance of CPAP and STIL in centriole formation, and suggest that one reason for the development of microcephaly may be defects in the proper formation of centrioles." (PMID 24052813, 2013).
Seckel syndrome (26 papers, 2012 to 2025). A rare autosomal recessive inherited syndrome caused by mutations in the ATR gene, RBBP8 gene, CENPJ gene, CEP152 gene, CEP63 gene, NIN gene, DNA2 gene, or TRAIP gene. "From the Seckel syndrome patient with CPAP mutation, brain organoids have been derived that display premature neuronal differentiation and smaller size." (PMID 36518994, 2022). "Brain organoids derived from a Seckel syndrome patient with CPAP mutation display a smaller size and premature neuronal differentiation." (PMID 33195219, 2020). "CPAP mutations cause primary autosomal recessive microcephaly and Seckel syndrome." (PMID 28396859, 2017). "Both ASPM and WDR62 were found to interact with the centrosomal proteins CEP63, responsible for a form of Seckel Syndrome, and with CENPJ/CPAP/Sas-4, which is another MCPH protein (MCPH6)." (PMID 36980263, 2023). "Mutations in centrosomal proteins, such as CENPJ/SAS4/CPAP or CEP63, were also implicated in Seckel syndrome." (PMID 35133277, 2022). "Disruption of the centromere protein J gene, CENPJ (CPAP, MCPH6, SCKL4), which is a highly conserved and ubiquitiously expressed centrosomal protein, has been associated with primary microcephaly and the microcephalic primordial dwarfism disorder Seckel syndrome." (PMID 23166506, 2012).
Primary microcephaly (10 papers, 2007 to 2022). Head circumference below 2 standard deviations below the mean for age and gender at birth. "The most cause of primary microcephaly is genetic, which is regulating the cilium caused by autosomal recessive mutations such as CENPJ, CPAP, MCPH1, ASPM, CDK5RAP2, and WDR62 that genes also regulate centrosomes assembly." (PMID 36518994, 2022).
autosomal recessive primary microcephaly (9 papers, 2012 to 2023). Autosomal recessive primary microcephaly (MCPH) is a rare genetically heterogeneous disorder of neurogenic brain development characterized by reduced head circumference at birth with no gross anomalies of brain architecture and variable degrees of intellectual impairment. "CPAP overexpression leads to abnormal cell division, whereas mutations in CPAP can cause autosomal recessive primary microcephaly, characterized by a marked reduction in brain size." (PMID 26506005, 2015). "CPAP was identified as a regulator of brain size and its mutation causes autosomal recessive primary microcephaly (MCPH) and Seckel syndrome." (PMID 37237337, 2023). "Autosomal primary recessive microcephaly (MCPH) is a disorder in neurogenesis caused by at least nine genes, six of which encode centrosome components (CEP63, CEP135, CEP152, CDK5RAP2/Cnn, CPAP /MCPH6, and STIL/MCPH7) and two encode proteins associated with spindle poles (ASPM and WDR62)." (PMID 30687396, 2018).
breast carcinoma (3 papers, 2015 to 2024). "The unchecked cell proliferation observed in luminal and HER2-positive breast cancer subtypes is thought to be associated with deregulation of centrosome activity mediated by CPAP/CENPJ." (PMID 38606093, 2024). "A variety of cancers, including breast cancer, have been linked to overexpression in CPAP/CENPJ." (PMID 38606093, 2024). "Understanding the specific roles of CPAP/CENPJ in breast cancer subtypes provides valuable insights for the development of targeted therapeutic approaches in the future." (PMID 38606093, 2024).
hepatocellular carcinoma (3 papers, 2016 to 2020). A malignant tumor that arises from hepatocytes. "SUMO1-modified centrosomal protein P4.1-associated protein (CPAP) SUMOylation increases NF-κB activity by collaborating with HBx proteins in HBV-related hepatocellular carcinomas (HCCs)." (PMID 26993772, 2016). "Centrosomal P4.1-associated protein (CPAP) is overexpressed in hepatocellular carcinoma (HCC) and positively correlated with recurrence and vascular invasion." (PMID 31511651, 2020). "CPAP is overexpressed in HBV-associated hepatocellular carcinoma (HCC); however, the interaction between CPAP and HBx in HBV-HCC remains unclear." (PMID 31170980, 2019).
prostate carcinoma (2 papers, 2019 to 2021). A carcinoma that arises from epithelial cells of the prostate gland. "It is postulated that cPAP levels correlates inversely to progression rates for prostate cancer." (PMID 34065557, 2021). "However, in prostate cancer, it is shown that cPAP concentrations decrease in comparison to normal adjacent tissue." (PMID 34065557, 2021). "As is claimed, cPAP has a growth-suppressing effect and it is due to its cellular protein tyrosine phosphatase activity and both PAP mRNA and protein levels are decreased or absent in prostate carcinoma tissue." (PMID 30809318, 2019).
Hepatitis (1 paper, 2021). Inflammation of the liver. "Blockade of the pathways involved in CPAP-mediated CCL-16 expression or inhibition of the interaction between CCL-16 and its receptors may provide a novel strategy in hepatitis and HCC therapies." (PMID 34686650, 2021).
lung carcinoma (1 paper, 2022). "The association of CPAP with MT is required for centrosome clustering in breast and lung cancer cells." (PMID 35803737, 2022).
metastatic tumor (1 paper, 2021). "Basal level of phospho-EGFR upon CPAP depletion was found to be profoundly higher in mesenchymal cell-line UM-SCC-74B which was derived from a recurrent metastatic tumor and in an OSCC cell-line with epithelial phenotype (SCC-Cal27)." (PMID 33889303, 2021).
neuroblastoma (1 paper, 2023). Neuroblastoma (NB) is the most common solid, extracranial childhood tumor. "We have shown previously by proteomic studies that DYX1C1 interacts with CPAP (Centrosomal-P4.1-associated protein, Centromere protein J (CENPJ)) in the neuroblastoma cell line SH-SY5Y." (PMID 37237337, 2023).
oral cancer (1 paper, 2021). "All three oral cancer cell-lines, with epithelial and mesenchymal phenotypes that were stably expressing CPAP-shRNA showed elongated morphology, a key feature of EMT, compared to control shRNA expressing cells." (PMID 33889303, 2021). "Stable CPAP depletion was performed in 3 oral cancer cell-lines with: 1) an epithelial phenotype (SCC-Cal27), 2) a mesenchymal phenotype of primary tumor origin (UM-SCC-74A), and 3) a mesenchymal phenotype of recurrent tumor origin (UM-SCC-74B)." (PMID 33889303, 2021). "On the other hand, we found that CPAP protein levels were higher in EGF treated OSCC cells as well as in oral cancer tissues, suggesting that the frequently reported aberrant centriolar features of tumors are potentially a consequence, but not the cause, of tumor progression." (PMID 33889303, 2021).